INS (insulin)
Diseases named in the same sentence as INS in open-access papers (continued):
Sharing a sentence is not in itself a finding about the gene and the disease.
diabetes (continued). "Because of their association with diabetes mellitus, we also calculated estimates for insulin sensitivity and β-cell function to examine whether the state of low fasting insulin was a consequence of reduced production due to impaired β-cell function and preclinical diabetes mellitus." (PMID 29997193, 2018). "Since this variability is largely influenced by the absorption of insulin, a deeper understanding of the factors affecting the absorption of insulin from the subcutaneous tissue is necessary in order to improve glycaemic control and the long-term prognosis in people with diabetes." (PMID 30116732, 2018). "Diabetes mellitus (DM) posting one of the most common chronic diseases develops generally in individuals with insulin resistance in insulin target tissues and impaired insulin secretion from pancreatic β-cells in the presence of appropriate genetic and environmental factors." (PMID 30442870, 2018). "Hence, complications of diabetes are common and increasingly more patients require insulin therapy." (PMID 29508275, 2018). "Based on these findings, to understand molecular alterations in renal insulin signaling pathway and antioxidant systems in diabetes and in vivo effects of resveratrol, we hypothesized that diabetes-related modifications in renal tissues could be returned to normal conditions with resveratrol." (PMID 30602713, 2018). "Overall, our findings raise the possibility that eGFR > 1 SD may be an early predictor of dysglycemia and pre-diabetes, a possibility that could be further explored by investigating the relationships among post-challenge glucose, insulin levels and kidney function in youths." (PMID 29505614, 2018). "Additionally, hyperglucagonaemia could oppose insulin actions and increase hepatic glucose output, a mechanism described in diabetes." (PMID 30123187, 2018). "ROS level elevation in diabetes may be promoting glycation of proteins, glucose oxidation and increased lipid peroxidation leads to damage of enzymes, cellular machinery, and also increased insulin resistance due to oxidative stress." (PMID 30622608, 2018). "In contrast, high but not low insulin was associated with a higher risk of diabetes (column 3)." (PMID 29997193, 2018). "Diabetes mellitus (DM) is a metabolic disease characterized by hyperglycemia, due to the defects in insulin secretion and impaired insulin resistance." (PMID 30254714, 2018). "Importantly, these findings also led to the proposition that drugs currently used to overcome peripheral insulin resistance in diabetes may be repurposed to rescue brain insulin signaling in AD." (PMID 30542257, 2018). "For each patient, the SG values obtained at the time of scanning greatly influence the patient’s everyday diabetes treatment; i.e., patients may misjudge how to treat themselves (for example, treating themselves as being hypoglycemic or increasing/decreasing the insulin dosage)." (PMID 30100926, 2018). "However, considering that glucose control by insulin is the main therapy for diabetes, whether a clinical dose of statin would be protective in cases where blood glucose is not controlled remains unclear." (PMID 29682576, 2018). "Therefore, Hex may serve as a drug in the treatment of diabetes to recover normal insulin and GH profiles." (PMID 30297647, 2018). "HbA1c ≥10% represents poor glycaemic control and is an indicator for administering insulin treatment in DM patients with TB as recommended by the Union and World Diabetes Foundation." (PMID 30383776, 2018). "Diabetes mellitus (DM) is a chronic metabolic disease characterized by hyperglycemia due to the inability of insulin-dependent cells to effectively take up glucose." (PMID 29315243, 2018). "In men, filling out the EUROPEP questionnaire at the general practice, using insulin, not having some problems with diabetes self-care and less coffee consumption were associated with a better patient evaluation of care, as measured with the EUROPEP questionnaire." (PMID 29636042, 2018).
diabetes (continued). "Such a “three-way”, insulin/IGF-driven interaction between exocrine/cancer cells, endocrine pancreas, and the stroma may be key to understanding the progression of PDAC and of PDAC-associated diabetes." (PMID 29475434, 2018). "Diabetes mellitus (DM) is a metabolic disease characterized by abnormal glucose homeostasis and defects in insulin metabolism." (PMID 29850600, 2018). "Furthermore, due to the high incidence of diabetes in the local south-east asian population, we postulate that our findings also be contributed by the increased prevalence of insulin insensitivity, impaired fasting glucose and pre diabetes in the non-diabetic population." (PMID 29883468, 2018). "However, insulin injection therapy degrades the quality of life in patients with diabetes." (PMID 30285859, 2018). "Diabetes Mellitus (DM) is a complex metabolic disorder characterized by abnormal secretion and/or activity of insulin." (PMID 30108648, 2018). "Therefore, antagonizing the GPR44/DP2 pathway in T2DM to restore insulin secretion via a potentially disease driving mechanism may be an opportunity to develop a disease modifying drug in diabetes." (PMID 30557325, 2018). "If INS and the IR both glycated rapidly under hyperglycemic conditions, then a combination of glycated INS and glycated IR could produce significantly reduced IR activation even in the presence of normal amounts of IR and stimulate the over-expression of INS that is observed in diabetes." (PMID 29207492, 2017). "Interestingly, the large reductions in both fasting and non-fasting glucose levels in humans and rats treated with GPR40 agonists were accompanied by very modest increases insulin secretion that were observed in diabetics only under conditions of hyperglycemia (i.e. glucose challenge)." (PMID 28542610, 2017). "However, it is common that diabetes professionals and, even more, patients with diabetes focus their attention on the amount of carbohydrates on which they balance insulin therapy paying less attention to the overall diet, in particular to foods representing the main source of micronutrients." (PMID 29109962, 2017). "However, it is still difficult to evaluate the impact of the impaired insulin secretion consecutive to Abcg1 deficiency in diabetes since glucose intolerance was not a common feature in Abcg1−/− mice." (PMID 28869506, 2017). "Thus, our results clearly show TFG in β-cell to control insulin secretion in vivo by multiple mechanisms, which could at least partially explain the high coincidence of diabetes mellitus and HMSN-P." (PMID 29026155, 2017). "Although some phenotypic markers are known to predispose patients to hypoglycemia, its predictors in insulin-treated diabetes have not been well studied, especially when these patients are followed on an ambulatory basis and have not been actively enrolled in a study." (PMID 28913365, 2017). "Diabetes mellitus (DM) is a chronic disease of the human metabolic system regarding the malfunction in the production and utilization of insulin hormone." (PMID 32025098, 2017). "Furthermore, this analysis indicates that aging leads to perturbations in pathways associated with energy metabolism (i.e., oxidative phosphorylation, glucose, and fatty acid metabolism), diabetes (synthesis and function of insulin, IGF, and ghrelin), immune response and protein synthesis." (PMID 28649426, 2017). "Thus, physical exercise facilitates glucose metabolism and its efficiency, improving glycemic control, which can be observed by the lower basal and postprandial insulin concentrations and the reduction of glycated hemoglobin in physically active diabetics when compared to sedentary patients." (PMID 28400914, 2017). "In the murine model of diabetes used in the present study, insulin secretion was limited by the pancreotoxic effect of alloxan, so glycemia increased from 140–155 to 340–380 mg/dL, and insulin administration (5 IU/kg) reduced blood glucose by 35% at the time of administration." (PMID 28397755, 2017).
diabetes (continued). "These new HI-ligand complexes could provide both insulin and free radical scavenger release over a certain period of time after entering blood stream while the beneficial effects of ascorbic acid in diabetes mellitus, and its health complications have been already demonstrated." (PMID 28829407, 2017). "Thus insulin treatment may be a factor in the diabetes group having a lower level of DHEA-S concentration than in a population not taking insulin." (PMID 28553251, 2017). "The difference between diabetes and other chronic disease types regarding self-monitoring could be explained by the fact that for diabetes patients self-monitoring is recommended as an integral component of their treatment (particularly for patients using insulin)." (PMID 28320330, 2017). "Diabetes mellitus (DM), commonly known as diabetes, is a group of metabolic diseases characterized by chronic hyperglycemia due to problems with insulin secretion, insulin action or both." (PMID 28379204, 2017). "Here we investigate the effects of exogenous administration of FGF21 to obese and insulin-resistant NZO mice, and evaluate the potential of the diabetes-susceptible NZO mouse as an animal model to study endogenous FGF21 actions in regard to the prevention of diabetes in the future." (PMID 28770320, 2017). "Diabetic gastroparesis is a common complication of diabetes mellitus (DM) that is characterized by decreased serum insulin and insulin-like growth factor-1 (IGF-1)." (PMID 28931726, 2017). "Later, the issue of fat distribution and its relationship to the predisposition of atherosclerosis and diabetes came to the center of interest in connection with the first evidence that some types of diabetes are not related to insulin secretion but to insulin resistance." (PMID 29048380, 2017). "Diabetes mellitus (DM) is a glucose metabolism disease characterized by chronic hyperglycemia resulting from defects in insulin secretion, insulin action, or both." (PMID 28926600, 2017). "In addition, fatty acids are independent predictors of progression to diabetes and impair insulin actions via mechanisms including the Randle cycle, accumulation of intracellular lipid derivatives (eg, diacylglycerol and ceramides), oxidative stress, inflammation, and mitochondrial dysfunction." (PMID 28542544, 2017). "Diabetes mellitus (DM) is characterized by hyperglycemia due to disturbance in the metabolism of carbohydrates, fats, and proteins, resulting from defects in insulin secretion, insulin action, or both." (PMID 28085064, 2017). "Given glucose (but not fructose) rapidly elevates plasma insulin, Australian formulations may affect risk for metabolic diseases, including diabetes, in a manner that is distinct from high-fructose drinks, which promote lipid accumulation." (PMID 28956823, 2017). "Hence, using insulin sensitive pharmacological drugs may have positive properties on Type-1 diabetes mellitus treatment and improvement of metabolic control." (PMID 28811795, 2017). "Diabetes mellitus (DM) is a complex disease that results from failure of β-cells to secrete enough insulin to maintain normoglycemia." (PMID 28912479, 2017). "However the next period of chronic obesity may shift to diabetes by creating a vicious cycle between ahead growing FFAs (as in day and night periods) and insufficient increment of insulin production, which cannot compensate for the increased IR-threshold." (PMID 28884000, 2017). "However, there is yet no effective cure for diabetes and the available drugs and insulin currently used in managing the disease are associated with multiple undesirable side effects." (PMID 29216879, 2017). "Furthermore, since pre-diabetes and diabetes was associated with reduced rather than increased adipose tissue, it is likely that reduced insulin secretion due to MRDM rather than insulin resistance explains most the associations we present." (PMID 28137307, 2017).
diabetes (continued). "Diabetes mellitus (DM) is a metabolic disorder characterized by hyperglycemia resulting from a defect in the secretion of insulin and/or the impairment of its action." (PMID 29069143, 2017). "Studies show that more than half of patients with diabetes are not compliant to oral medications and insulin, and that non-adherence is consistently associated with poor glycemic control, where HbA1c level was 0.4–0.7% higher in non-adherent than in adherent patients." (PMID 28666031, 2017). "Based on our findings and the results from previous studies, insulin treatment could be plausible means of preserving muscle function while also improving the glycemic control of patients with diabetes who are affected by low muscle mass and strength in the lower extremities." (PMID 28246927, 2017). "Therefore, to discriminate the hypoglycemic effect of the endogenous insulin by teuhetenone A in the mice and to determine the antidiabetic effect, diabetes was induced pharmacologically with 200 mg/kg alloxan (intraperitoneally) in eight groups of five mice each." (PMID 28397755, 2017). "The management of diabetes mellitus (DM) requires a combination of lifestyle interventions, dietary modifications, and anti-diabetic medications, with subcutaneous injections of insulin required for type 1 DM." (PMID 28606115, 2017). "Diabetes mellitus, one of the major public health problems worldwide, is a metabolic disorder of multiple etiologies distinguished by a failure of glucose homeostasis with disturbances of carbohydrate, fat and protein metabolism as a result of defects in insulin secretion and/or insulin action." (PMID 28464813, 2017). "Also, residual insulin secretion has been proposed as a mean of classifying diabetes." (PMID 29296240, 2017). "Although the efficacy of anti-diabetic drug regimes might be limited in ability to prevent DHD, exercise is emerging as having addictive effects for improving hyperglycaemia and insulin sensitivity by normalizing myocardial oxidative stress, lipotoxicity and systemic inflammation in diabetes." (PMID 28086863, 2017). "These pleiotropic effects of atorvastatin which led to the adjustment of glucose homeostasis and renoprotection observed in this study might be due to the additive effect of atorvastatin and insulin in controlling metabolic parameters and subsequently protect kidney dysfunction in diabetes." (PMID 29051569, 2017). "Moreover, sulfonylurea therapies could lower the blood glucose levels and raise plasma insulin levels in the untreated patients with diabetes mellitus and postprandial blood glucose levels and low plasma insulin levels." (PMID 28386567, 2017). "Diabetes mellitus (DM) is a metabolic disorder characterized by hyperglycemia due to defects in insulin secretion or action." (PMID 28836407, 2017). "Another group suggested that the insulin producing pancreatic β-cells are among the targets for arsenic exposure, and that the inhibition of GSIS (glucose stimulated insulin secretion) by the methylated metabolites may be the key mechanism of arsenic-induced diabetes." (PMID 28108741, 2017). "Moreover, the dose of insulin detemir applied in this paper caused an increase in the concentration of this adipokine both in men and in women, reflecting the beneficial influence of the therapy with the applied insulin analogue on the impaired systemic metabolism in the course of diabetes." (PMID 28758947, 2017). "In different experimental animal models, such as rats with alloxan-, streptozotocin- (STZ-), or STZ-nicotinamide-induced diabetes, oral administration of curcumin resulted in a reduction in body weight, blood glucose, and glycosylated hemoglobin levels and improvement of insulin sensitivity." (PMID 29164155, 2017). "Type 2 diabetes mellitus (T2DM), which accounts for 90–95% of all DM cases, results from a combination of insulin resistance and dysfunction of insulin-producing pancreatic beta cells." (PMID 28515792, 2017).
diabetes (continued). "Furthermore, several randomized controlled trials reported that physical activity could improve insulin sensitivity and glucose tolerance and then delay the onset of diabetes in subjects with prediabetes." (PMID 28367452, 2017). "Diabetes is caused by the lack of release or action of insulin." (PMID 28859155, 2017). "However, regardless of the mutation or diabetes status, these insulin-producing cells are immature, a common downfall off most current β-cell differentiation protocols." (PMID 28684784, 2017). "Thus, we speculated that abnormal insulin regulation in diabetes may also affect the predictive role of plasma H19 for CAD in our study." (PMID 28790415, 2017). "Exclusion of 0.5–1 year of insulin use, or analysis of short-term use only, may preclude observing the actual dynamics of cancer incidence among insulin users and thus may hinder a better understanding of the nature of the link between diabetes and cancer." (PMID 28573394, 2017). "In addition, diabetes exists as a comorbidity for the majority of all myocardial infarction mortalities due from occluded coronary circulation, myocardial energy dysregulation, and insulin resistance." (PMID 29209228, 2017). "The duration of diabetes mellitus, the length of dual anti-platelet therapy use and the use of other cardiovascular and oral anti hypoglycemic medications as well as the use of insulin therapy could also have had an effect on the outcomes between male and female patients with diabetes mellitus." (PMID 28750607, 2017). "Genomic expressions in insulin signaling and integrated pathways may manifest themselves and to interrupt any one of these genes could develop the clinically significant insulin resistance and diabetes." (PMID 28179884, 2017). "Indeed, it was reported that insulin sensitizers may attenuate the decline in muscle mass in patients with diabetes." (PMID 28246927, 2017). "Glycation of the IR may therefore provide a mechanism by which INS resistance develops in diabetes." (PMID 29207492, 2017). "This study highlights the current status with respect to quality of insulin-related information communicated at the point of discharge, and the types of problems that may occur on the interface for patients with insulin-treated diabetes." (PMID 28852529, 2017). "Although the present work is aimed at shedding new light on the physiological storage state of this hormone, it may also open ways to novel approaches in medical formulations of insulin, toward its more desired closer to in vivo profile during subcutaneous injections administered in diabetes." (PMID 28348075, 2017). "Another study also reported that miRNAs were significantly differently expressed in proximal renal tubular cells due to exposure to calcium oxalate monohydrate crystal and some of them might be involved in the insulin signaling pathway and type 2 diabetes mellitus." (PMID 29392139, 2017). "Ensuring that all professionals have expertise in diabetes and dementia would be difficult, and a collaborative practice is likely to be necessary for people with both conditions, particularly for more complex cases such as people who are insulin-dependent or those with advanced dementia." (PMID 28750628, 2017). "Moreover, the leptin-induced overexpression of IGFBP-2 has been shown to reverse diabetes in insulin-resistant obese mice and hyperinsulinemic clamp studies showed a threefold improvement in hepatic insulin sensitivity following IGFBP-2 treatment of ob/ob mice." (PMID 29422987, 2017). "Stringent glycemic control by using insulin as a replacement or in addition to oral hypoglycemic agents (OHAs) has been recommended for people with tuberculosis and diabetes mellitus (TB-DM)." (PMID 29059214, 2017).